LEAP2 (liver enriched antimicrobial peptide 2)
Diseases named in the same sentence as LEAP2 in open-access papers (continued):
Sharing a sentence is not in itself a finding about the gene and the disease.
bacterial infection (9 papers, 2019 to 2025). "The liver-expressed antimicrobial peptide 2 (LEAP2) family is an important group of antimicrobial peptides (AMPs) involved in vertebrate defence against bacterial infections." (PMID 40082911, 2025). "This structural difference enhances the antibacterial activity of linear LEAP2, making it more effective against bacterial infections." (PMID 38835040, 2024). "AjCRFB5a functions in the host immune response to bacterial infection by activating antimicrobial peptide LEAP2, and it works as a positive regulator of host antiviral immune responses by activating IRF3 and IRF7-mediated type I IFN signaling pathways." (PMID 37835763, 2023). "Similarly, in the golden pompano (Trachinotus ovatus), LEAP2 is predominantly expressed in the liver, spleen, and kidneys with significant upregulation in response to bacterial infections such as Edwardsiella tarda and Streptococcus agalactiae." (PMID 40082911, 2025). "Our findings together showed that AjCRFB5a participates in the host immune response to bacterial infection by inducing antimicrobial peptides mediated by LEAP2 and favorably modulates host antiviral immune responses by activating IRF3 and IRF7-driven type I IFN signaling pathways." (PMID 37835763, 2023). "Elevated CSF LEAP2 concentrations appear to reflect bacterial infection in the CNS." (PMID 33811478, 2021). "Although it is unclear whether LEAP2 enters the brain by the same mechanism as ghrelin, LEAP2 levels rise in the human CNS during bacterial infection." (PMID 33811478, 2021). "Interestingly, LEAP2 is upregulated in response to bacterial infections such as Salmonella." (PMID 37799512, 2023). "LEAP2 is a critical AMP in the host’s innate immune response, particularly in combating bacterial infections." (PMID 40082911, 2025). "Liver-expressed antimicrobial peptide 2 (LEAP2) is an important AMP found in vertebrates, playing a central role in the innate immune system by protecting against bacterial infections." (PMID 40082911, 2025). "Thus, increased LEAP2 levels during bacterial infection may be applicable as a potential biomarker." (PMID 33811478, 2021). "Although there is still no clear evidence for this, in acute phase responses from bacterial infections of H. pylori, LEAP2 expression is elevated." (PMID 32268520, 2020).
metabolic disorders (8 papers, 2021 to 2026). "Here, we show that overexpression of LEAP2 in the ARC through adeno-associated virus (AAV) reduced food intake and body weight in wild-type (WT) mice fed chow and a high-fat diet (HFD) and improved metabolic disorders." (PMID 36387867, 2022).
neurological diseases (1 paper, 2021). "This original study describes the identification of liver‐expressed antimicrobial peptide 2 (LEAP2), an antimicrobial peptide, in human CSF, and is the first to measure CSF LEAP2 in neurological disorders." (PMID 33811478, 2021). "We measured LEAP2 concentrations in the CSF of 35 patients with neurological disorders." (PMID 33811478, 2021). "Previous studies have not shown whether LEAP2 is present in human cerebrospinal fluid (CSF), and if so, whether its levels are altered in neurological disorders." (PMID 33811478, 2021).
tumor (1 paper, 2025). "Taken together, these findings suggested that tumor-derived LEAP2 might contribute to elevated circulating levels of LEAP2." (PMID 41488138, 2025). "We focused on whether circulating LEAP2 levels are altered in patients, how they relate to insulin and ghrelin, and whether LEAP2 is expressed in tumor tissues." (PMID 41488138, 2025). "Given that ghrelin inhibits insulin release, it will be important to determine whether LEAP2 has the opposite effect, potentially enhancing insulin secretion or promoting tumor proliferation." (PMID 41488138, 2025). "Extensive tumor expression of LEAP2 indicates both hepatic and tumor-derived contributions." (PMID 41488138, 2025). "Moreover, LEAP2 levels declined in three of four cases after resection, suggesting that tumor removal may reduce circulating LEAP2." (PMID 41488138, 2025).
LEAP2 also shares sentences with these, for which no sentence is quoted: cancer (3 papers); prediabetes (3); Anorexia (2); Hyperglycemia (2); metabolic syndrome (2); age (1); alcohol abuse (1); aseptic meningitis (1); colitis (1); Glucose intolerance (1); Hypercholesterolemia (1); hypothalamic disorder (1); memory loss (1); multiple sclerosis (1); neurodegenerative disease (1); non-alcoholic fatty liver disease (1); overnutrition (1); psychosomatic disorder (1); viral hepatitis (1).